CD177 (CD177 molecule)
Diseases named in the same sentence as CD177 in open-access papers (continued):
Sharing a sentence is not in itself a finding about the gene and the disease.
Sepsis (continued). "The candidate hub genes (CD177, CYSTM1, and MMP8) were identified, and the nomogram was constructed for pediatric sepsis diagnosis." (PMID 37115484, 2023). "Other biomarkers also correlate with outcome/prognosis e.g., CD177, FGF13, GRB10 and PPARG in both SIRS and sepsis." (PMID 38332914, 2023). "Providing external validation to our findings, several genes, such as CD177, ARG1 (arginase), MMP9, OLAH and ADM have been described previously as having important inflammatory roles in sepsis." (PMID 38332914, 2023). "And many of these genes (such as CD177, S100A12, and CLEC4D) played a critical role in sepsis pathology." (PMID 35739592, 2022). "ELANE, MPO, CD177, OLFM4 and OLAH gene expression were found to be comparable in both the groups sepsis and sterile inflammation indicating that neutrophil response to both bacterial infection and tissue injury involved upregulation of these genes." (PMID 34552111, 2021). "CD177 expression was observed to be highly elevated in adult and pediatric SIRS, sepsis, septic shock and resolved SIRS." (PMID 32318053, 2020). "Gene entities shared between sepsis and severe sepsis response hubs are; TDRD9 – LIN7A, GPR84 – ENTPD7, PYCT1A and ZDHHC19, CD177 – DDAH2 and RGL4, SLC16A3 – DENND3 and MBD6, MYL9 – CMTM5, ITGB3, ITGA2B, NRGN, SELP and TREML1." (PMID 32318053, 2020). "Genes that were expressed at high levels in MBC and sepsis patients compared with HC N cells were relevant to immunosuppression and metastasis (ARG1, MMP8, TLR5, and CD177) (green)." (PMID 32958605, 2020). "CD177 also exhibited strong direct connections to other hub entities GPR84 and TDRD9 in adult and pediatric sepsis and to GPR84 alone in pediatric septic shock and resolved SIRS." (PMID 32318053, 2020). "In adult sepsis there is indirect interaction between GPR84, CD177, and TDRD9 through EXOSC4 and with CD177 through NECAB1." (PMID 32318053, 2020). "Gene differential expression analysis between healthy controls and sepsis showed that genes such as ARG1, CD177, MMP8 and C19orf59 were upregulated." (PMID 33032623, 2020). "In adult sepsis, genes TDRD9, GPR84, and CD177 interacted via overlapped genes EXOSC4 (TDRD9 ↔ GPR84 ↔ CD177), ZDHHC19 (TDRD9 ↔ CD177) and NECAB1 (GPR84 ↔ CD177)." (PMID 32318053, 2020). "The profile is somewhat similar in pediatric sepsis with connections between GPR84 and TDRD9 directly and indirectly through instead DDAH2 and with CD177 through C19orf59 and RGL4." (PMID 32318053, 2020). "Some selected genes were significantly higher expressed in sepsis as compared with MBC samples (CD24, CD177, MMP8, and TLR5), and in MBC compared with sepsis (HLA-DRA, CSF1R, and AGAP6/9)." (PMID 32958605, 2020). "By regulating the activation of CD177+ neutrophils, ZDHHC19 may influence the severity of the immune response during sepsis and contribute to disease progression." (PMID 40666706, 2025). "Further, Ly6G antibody–mediated pulse labeling after sepsis induction with LPS did not reveal significant differences in CD177 expression in-between peripheral blood neutrophils labeled at different time points." (PMID 38517968, 2024). "Additionally, by comparing the expression profiles between disease samples and control samples, it was found that the expression levels of CD177, RNASE2, IRAK3, and S100A12 were significantly elevated in both IE and sepsis samples." (PMID 38332910, 2023). "CD177, ARG1, FAM20A, PCOLCE2, SLC51A, MMP9, were identified as most significantly upregulated in both SIRS and Sepsis on Day1, compared with healthy controls, with CD177 and ARG1 consistently higher for both SIRS and Sepsis at this and across all timepoints to discharge." (PMID 38332914, 2023). "Moreover, to ascertain whether these diagnostic genes also possessed good clustering capabilities across different sepsis groups, an intersection was made between the machine learning-selected diagnostic genes and key cluster genes, resulting in two intersecting genes (IRAK3, CD177)." (PMID 38332910, 2023).
Sepsis (continued). "Similarly, the genes screened by WGCNA such as CD177, S100A12, and CLEC4D have also been described to be important in the pathogenesis of sepsis." (PMID 35739592, 2022). "Stratification of ACLF samples based on the presence or absence of sepsis demonstrated higher numbers of CD177+ neutrophils in the ACLF sepsis biopsies although CD16+ neutrophils were comparable (p value 0.0635 and p value 0.2222 respectively)." (PMID 34552111, 2021). "We also observed that in ACLF, patients with sepsis had greater number of CD177+ neutrophils in liver tissues as compared to patients without detectable sepsis (sterile inflammation) (p = 0.0635)." (PMID 34552111, 2021). "The majority of these clusters were not connected in most disease and control states, except for adult sepsis and adult SIRS with the gene clusters for TDRD9, CD177, GPR84, PCOLCE2, FGF13 and SLC16A3 interconnected at various points, either directly or through overlapped gene connections." (PMID 32318053, 2020). "However, the sepsis patients were also characterized by a constant CD177 negative neutrophil subset, CD177 was coexpressed with protease 3, and circulating neutrophils in addition showed decreased CD10 levels with a significant inverse correlation between CD177 and CD10 protein levels." (PMID 37048076, 2023).
viral infection (18 papers, 2017 to 2025). "Interestingly, proteomics directly revealed details on the immune defense against viral infections, including drastic increase in antigen CD177, Integrin alpha‐M (ITGAM) as well as the complex‐forming E3 ubiquitin‐protein ligase DTX3L and PARP9." (PMID 37519267, 2023). "In detail, levels of CD177, a marker for neutrophil activation, and CXCL9 were elevated, while DDX58, also known as RIG-I, a sensor for a viral infection that induces type I IFN production, was found to be decreased in aIFNpos patients." (PMID 38421006, 2024).
colorectal cancer (15 papers, 2013 to 2025). A primary or metastatic malignant neoplasm that affects the colon or rectum. "In summary, we identified CD177 as a potential predictive biomarker for the response to bev-containing anti-cancer therapy in colorectal cancer patients and characterise a potential causal chain linking hypoxia to neutrophil recruitment upon bev treatment." (PMID 30377339, 2019). "It is uncertain whether CD177-null individuals are susceptible to certain diseases, but CD177-positive neutrophils seem to suppress tumorgenesis in epithelial cells and improve survival in patients with colorectal cancer." (PMID 38474126, 2024). "CD177 overexpression was significantly correlated with a favorable prognosis for gastric cancer and CD177+ neutrophils suppress epithelial cell tumorigenesis in colitis-associated cancer and predict good prognosis in colorectal cancer, pointing to a protective role of CD177 in cancer." (PMID 39131159, 2024). "Furthermore, CD177 expression on neutrophils, epithelial cells, and regulatory T cells in solid tumors has been associated with tumor invasion, disease stage, therapeutic responses, and patient survival in various cancers, including gastric, breast, and colorectal cancer (CRC)." (PMID 41142798, 2025). "Key transcripts, such as MPO, FCGR1A, DEFA4, and CD177, have been highlighted as potential biomarkers of colorectal cancer, underscoring the role of immune dysregulation in tumor development and progression." (PMID 40003985, 2025). "This study identified and validated a reproducible five-gene panel—DLG5, CD177, SH2D1B, NQO2, and KRT73—derived from whole-blood RNA, with strong diagnostic relevance for colorectal cancer (CRC)." (PMID 41373777, 2025). "We observed the presence of CD177 in 15-25% of TI Treg cells, including breast, renal, lung, and colorectal cancers." (PMID 34599187, 2021). "Notably, IFI27 was linked to the symptomatic non-disease control group, DEFA4 to the non-advanced adenoma group, MPO to the advanced adenoma group, and CD177 to the colorectal cancer group." (PMID 40003985, 2025). "Notably, CD177 overexpression has been observed in the tissues of patients with inflammatory bowel disease and colorectal cancer." (PMID 38226808, 2024). "CD177 has been proven to predict the benign prognosis of colorectal cancer." (PMID 33193652, 2020). "Here we report that the absence of CD177-positive neutrophils in colorectal cancer metastasis identifies patients with a significant survival advantage in response to bev therapy." (PMID 30377339, 2019).
prostate carcinoma (15 papers, 2006 to 2024). A carcinoma that arises from epithelial cells of the prostate gland. "Three genes (CD177, DUOX1, and AOC1) were downregulated in prostate cancer through the analysis of bioinformatics data; the roles of both CD177 and DUOX1 in prostate cancer have been reported." (PMID 35922412, 2022). "The roles of CD177 and DUOX1 in prostate cancer have been comprehensively reported; however, how AOC1 is involved in prostate cancer remains unclear." (PMID 35922412, 2022).
colitis (14 papers, 2016 to 2025). Inflammation of the colon. "Administration of DMF substantially ameliorated colitis development in Cd177−/− mice, characterized by mild weight loss, lowered histological damage, and more intact epithelial barrier integrity." (PMID 36729914, 2023). "Accordingly, colitis mice that are deficient in CD177 + neutrophils have a compromised intestinal barrier and increased colitis development." (PMID 35039631, 2022). "As a complementary approach, we orally infected WT and Cd177−/− mice with Citrobacter rodentium (CR, 2 × 109 CFUs/mouse), and found that Cd177−/− mice developed more severe colitis with more weight loss, impaired epithelial barrier integrity than WT controls after CR infection." (PMID 36729914, 2023). "Collectively, these results indicate that microbial dysbiosis plays an important role in modulating TCRγδ+CD8αα+ IEL expansion and functions in Cd177−/− mice during colitis." (PMID 36729914, 2023). "Consistently, supplementation of DMF unequivocally alleviated experimental colitis and restrained the overactivation of TCRγδ+CD8αα+ IELs in colitic Cd177−/− mice." (PMID 36729914, 2023). "Taken together, these data demonstrated that CD177+ neutrophils control the colitogenic TCRγδ+CD8αα+ IEL expansion during colitis." (PMID 36729914, 2023). "To this end, we induced acute colitis in Cd177−/− and WT mice with DSS insults and simultaneously depleted neutrophils with anti-Ly6G antibody intraperitoneally." (PMID 36729914, 2023). "Studies have confirmed that CD177+ neutrophils represent a functionally activated population and protect against IBD through increased bactericidal activity and that CD177−/− mice developed more severe colitis on DSS insults compared with wild-type mice." (PMID 37048616, 2023). "Consistent with the results from DSS-induced colitis, exposure to CR infection also caused an increase in TCRγδ+CD8αα+ IELs but a decrease in TCRαβ+CD4+·IELs in the colon of Cd177−/− mice compared with WT controls." (PMID 36729914, 2023). "CD177+ Neutrophils were reported to be a beneficial phenotypic adaptation in IBD colitis, with CD177-deficient mice developing more severe DSS colitis." (PMID 36009449, 2022). "We showed that α-TREM-1 induced CD177+ neutrophils in the blood of IBD patients and healthy controls, and that α-TREM-1-driven CD177+ neutrophils ameliorate mouse colitis." (PMID 33767714, 2021). "CD177 knockout mice develop more severe colitis induced by DSS and compromised intestinal barrier integrity than wild-type mice." (PMID 30473691, 2018). "We found aggravated mucosal damage and architectural distortion in the intestines of colitic Cd177−/− mice compared with WT controls, as manifested by aggravated histological lesions and damaged mucosal barrier, indicating that Cd177−/− mice developed more severe colitis under DSS insults." (PMID 36729914, 2023). "CD177+ BMDN transfer markedly attenuated colitis and restored goblet cell numbers." (PMID 33767714, 2021). "This association of neutrophils accumulation at the inflamed sites with CD177-dependent protection from colitis induced by DSS suggests these CD177+ neutrophils are anti-inflammatory and IBD-protective and appear to be distinct from pro-inflammatory LDGs found in SLE." (PMID 30473691, 2018). "The increase in expression of CD177 and CEACAM1, for instance, is closely related to colitis after ipilimumab treatment." (PMID 37304306, 2023). "The stimulation of triggering receptor expressed on myeloid cell (TREM)−1 with an agonistic antibody induced CD177 + neutrophils that produced NETs and IL22 and induced pathogen clearance and wound healing, alleviating colitis." (PMID 35039631, 2022). "We treated Cd177−/− and WT mice with DMF by oral gavage and induced colitis with DSS." (PMID 36729914, 2023). "Accordingly, the intestinal barrier is impaired in colitis mice lacking CD177+ neutrophils, and the development of colitis is accelerated." (PMID 37998356, 2023).
lung carcinoma (13 papers, 2004 to 2025). "CD177 is a glycosylphosphatidylinositol-linked cell surface protein that is heterogeneously expressed by neutrophils, and its expression is associated with good prognosis in breast, prostate, cervical, and lung cancers." (PMID 36338624, 2022). "In the previous study, the downregulated genes CASP10 and CD177 and the upregulated genes BAK1, ST14, CD82, and MUC4 were detected as biomarkers for lung cancer by the joint sparse regression model." (PMID 35923697, 2022). "Among genes that are suppressed, there are a number involved in the immune response, including CD177 and BST1, suggesting an impaired immune response in the airway of smokers with lung cancer." (PMID 25944280, 2015). "Indeed, although the number of samples is limited, we found a correlation between CD177 expression and KFP-tetramer binding to neutrophils of healthy donors, patients with COPD and lung cancer patients." (PMID 36275643, 2022).
autoimmune disease (11 papers, 2010 to 2025). A disorder resulting from loss of function or tissue destruction of an organ or multiple organs, arising from humoral or cellular immune responses of the individual to their own tissue constituents. "Similarly, the anti‐CD177 monoclonal antibody Hu‐AMLX7909 has been explored for its ability to selectively deplete proinflammatory low‐density granulocytes (LDGs) in autoimmune disorders like ANCA‐associated vasculitis." (PMID 39845896, 2025). "In summary, the expression of CD177 on neutrophils is significantly increased in the context of inflammation, autoimmune diseases, and certain tumors, correlating with the severity of inflammation and tumor prognosis." (PMID 41142798, 2025). "CD177 has shown good prospects in clinical application, especially in the early diagnosis and prognosis evaluation of infections, tumors and autoimmune diseases." (PMID 41142798, 2025). "Although such subsets are rarely identified in autoimmune diseases, some unique subsets of neutrophils, including low density granulocytes (LDGs) and CD177+ neutrophils, have been reported." (PMID 30473691, 2018). "- Neutrophils in certain autoimmune diseases may also be classified into different subsets, with low density granulocytes (LDGs) representing pro-inflammatory neutrophils and Gr-1high or CD177+ neutrophils exhibiting anti-inflammatory effects." (PMID 30473691, 2018). "Moreover, the proportion of CD177+ neutrophils has been shown to increase in various inflammatory conditions, such as bacterial infections and autoimmune disorders, suggesting that this subset may play a role in the pathogenesis of these diseases." (PMID 39845896, 2025). "Dysregulation of CD177+ neutrophils, resulting in immune overactivation, is a key mechanism in autoimmune diseases, and the mean fluorescence intensity (MFI) of CD177+ neutrophils may serve as a novel biomarker for assessing disease activity in SLE." (PMID 41142798, 2025). "The formation of the CD177/mPR3/GPR97 complex represents a crucial step in the activation of neutrophils; its dysregulation may contribute to the onset of inflammatory conditions or autoimmune diseases." (PMID 41142798, 2025). "Despite limited studies that have primarily identified variations in CD177 expression and its correlation with diseases in the context of tumors, inflammation, and autoimmune disorders, there is a lack of in-depth mechanistic research and large-scale, multicenter prospective studies for validation." (PMID 41142798, 2025).
gastric cancer (11 papers, 2011 to 2025). A primary or metastatic malignant neoplasm involving the stomach. "Immunohistochemical analysis of CD177, one of the up-regulated genes, was performed in human advanced gastric cancer specimens to evaluate the association with prognosis." (PMID 23899160, 2013). "Limited literature indicates a correlation between the loss of CD177 expression and poor prognosis in intestinal tumors, such as CRC, and gastric cancer." (PMID 41142798, 2025). "On immunohistochemical analysis of human gastric cancer tissues, CD177 was observed not only in the membranes and cytoplasms of infiltrated neutrophils, but also in gastric cancer cells of both well- and poorly-differentiated adenocarcinomas." (PMID 23899160, 2013). "Immunohistochemical analysis of CD177 in advanced gastric cancer specimens showed expression to be significantly correlated with a good prognosis and survival rate after surgery." (PMID 23899160, 2013). "Among 55 gastric cancer cases, moderate to strong expression of CD177 was observed in 33 (60.0%)." (PMID 23899160, 2013). "Studies have found that a high expression of CD177 on neutrophils in tumor tissues from CRC, gastric cancer patients, and a positive correlation with overall survival(OS) and disease-free survival." (PMID 41142798, 2025).